IL6 (interleukin 6)
Diseases named in the same sentence as IL6 in open-access papers (continued):
Sharing a sentence is not in itself a finding about the gene and the disease.
malaria (continued). "A subgroup analysis of Plasmodium species showed higher mean IL-6 levels in patients with uncomplicated malaria than in controls among studies that enrolled patients infected with P. falciparum only." (PMID 35396564, 2022). "For example, the study in Brazil31 enrolled patients with P. vivax for the comparison of mean IL-6 levels between patients with uncomplicated malaria and those with asymptomatic malaria." (PMID 35396564, 2022). "As expected, the IL-10/IL-6 ratio was lower in malaria group when compared to the coinfected, showing that in the coinfected the response was leaning more towards a suppressive profile." (PMID 35749690, 2022). "Results of the meta-analysis showed that patients with uncomplicated malaria had higher mean IL-6 levels than controls." (PMID 35396564, 2022). "The malaria group showed higher values of this cytokine compared with all other groups, demonstrating that IL-6 levels are highly stimulated during P. vivax infection." (PMID 35749690, 2022). "Systematic literature searches were conducted in PubMed, Web of Science, and Scopus until November 7, 2021 to obtain studies that documented IL-6 levels in patients with malaria." (PMID 35396564, 2022). "Differences in IL-6 levels between patients with uncomplicated malaria and controls were estimated using the available data from 17 studies." (PMID 35396564, 2022). "Two other studies in Burkina Faso43 and Gambia34 enrolled patients with P. falciparum for comparisons of mean IL-6 levels between patients with uncomplicated malaria and those with asymptomatic malaria." (PMID 35396564, 2022). "The present systematic review and meta-analysis aimed to compare the differences in IL-6 levels between several groups of patients with malaria and healthy control groups." (PMID 35396564, 2022). "Based on the results of our meta-analysis and studies that were included in the analysis, IL-6 levels were increased in patients with uncomplicated malaria compared to healthy controls." (PMID 35396564, 2022). "Subgroup analysis of the characteristics of the control groups had higher mean IL-6 levels in those with uncomplicated malaria than in healthy controls (P < 0.001, WMD = 42.02 pg/mL, 95% CI = 26.91–57.12 pg/mL, I2 = 98.9%, 14 studies)." (PMID 35396564, 2022). "Between them, TNF-α, interleukin 10 (IL-10) and IL-6 are molecules that can be a powerful inflammatory marker of severity during malaria." (PMID 35749690, 2022). "Our meta-analysis of the pooled evidence can be used to guide future studies in which IL-6 levels are measured during malaria outbreaks to monitor malaria severity." (PMID 35396564, 2022). "Differences in IL-6 levels between patients with uncomplicated malaria and asymptomatic malaria were estimated using the available data of three studies." (PMID 35396564, 2022). "Results showed that patients with uncomplicated malaria had higher mean IL-6 levels than controls (P < 0.001, WMD = 42.86 pg/mL, 95% CI = 30.17 − 55.56 pg/mL, I2 = 100%, 17 studies)." (PMID 35396564, 2022). "Collectively, data from these two reports support the idea that IL-6 and IL-21 play redundant roles in supporting Tfh cells during malaria, but are both independently important for supporting subsequent GC B cell responses." (PMID 36845571, 2021). "Based on these findings, severe malaria was significantly associated with declined CD4+ and CD8+ T cell counts, upregulation of IL-6 and high serum levels of oxidative stress biomarkers." (PMID 35223394, 2021). "Our study revealed serum IL-10 and IL-6 concentrations significantly elevated with increased in malaria density (p<0.0001)." (PMID 35223394, 2021). "The ratio between IL-10 levels and parasite density was 0.008 and 0.01 for clinical and asymptomatic malaria respectively, whereas for IL-6 the ratio was 0.0014 versus 0.00088, and for TNF-α 0.0014 versus 0.010." (PMID 34177883, 2021).
malaria (continued). "Polymorphisms in TNF-α and IL-6 genes, as well higher levels of these markers and of CXCL10 were linked to malaria clinical outcomes and pro-inflammatory activation in response to P. vivax." (PMID 34727121, 2021). "Many cytokines and chemokines (e.g., IL-6 and the complement system) have been associated with the neurocognitive sequelae of maternal infection, and future studies should expand the panel of inflammatory markers that could link malaria in pregnancy with neurodevelopment." (PMID 34582452, 2021). "Patients with bacteremia had lower circulating IL-10, TNF-α and IFN-γ and higher IL-6 concentrations, compared to clinical malaria." (PMID 34177883, 2021). "After using one-way ANOVA and Dunnett’s Multiple Posthoc to determine difference between control and the three groups, serum IL-10 and IL-6 concentrations significantly elevated with increase in malaria density (p<0.0001)." (PMID 35223394, 2021). "The cytokine/parasite density ratios also pointed in this direction as the IL-10/parasite density ratio was highest in asymptomatic malaria cases while the pro-inflammatory IL-6/parasite density ratio was highest in patients with clinical malaria." (PMID 34177883, 2021). "Previous studies demonstrate that high levels of IL-6 as well as TNF-α contribute to complications of malaria such as cerebral malaria." (PMID 34177883, 2021). "HBB is involved in the malaria reference pathway and downregulates IL-6, which is a key gene in the HIF-1 pathway." (PMID 34691141, 2021). "These together with the significant changes in the cytokine levels (IL-6 and IL-10) point to the debilitating effect of malaria on the immune system." (PMID 35223394, 2021). "In both malaria groups, IL-6 levels correlated significantly with parasite density (ρ = 0.49 and ρ = 0.48 respectively, p<0.001)." (PMID 33253198, 2020). "For children with microscopic asymptomatic malaria, IL-6 was found to positively correlate with TNF-α (r = 0.59, p < 0.0001), IL-4 (r = 0.39, p = 0.017), and IL-10 (r = 0.50, p = 0.002)." (PMID 33281757, 2020). "It is possible that haemozoin activated pro-inflammatory chemokines (i.e., IFN-γ, CXCL 10), and cytokines (i.e., TNF, IL-6) can contribute to M1 polarization in malaria, resulting in ALI/ARDS." (PMID 32414377, 2020). "Another study in India has recently shown that women with Pv malaria in pregnancy have more IL-6, TNF and IL-1β in peripheral plasma than uninfected pregnant women." (PMID 32365058, 2020). "IL-10 also strongly inhibits the production of cytokines such as TNF, IL-I and IL-6, which are involved in malaria pathology." (PMID 32758231, 2020). "High levels of pro-inflammatory cytokines have been associated with the development of clinical disease whereas increased levels of IL-6 have been observed in submicroscopic malaria in pregnancy." (PMID 33281757, 2020). "The IL-6/IL-10 ratio, indicating pro/anti-inflammatory balance, was significantly lower in asymptomatic children, compared to clinical malaria." (PMID 33253198, 2020). "Inflammatory chemokines CXCL10, CCL2, and CCL3 as well as cytokines, TNF-α, IL-8, and IL-6 were differentially expressed in individuals with different hemoglobin genotypes that were infected or uninfected with malaria parasites." (PMID 33424841, 2020). "The results indicate that differential expression of CXCL10, TNF-α, CCL2, IL-8, and IL-6 were tightly linked to hemoglobin genotype and severity of Plasmodium infection and that these cytokine levels may be predictive for susceptibility to severe malaria or SCD severity." (PMID 33424841, 2020). "In malaria, elevated IL-6 is found in patients with severe Plasmodium falciparum/vivax malaria and associated with development of cardiac complications." (PMID 33584641, 2020). "HIV-malaria coinfected pregnant women showed significantly higher levels of IL-6, IFN-γ, TNF-α, and blood pressure with reduced BMI value compared with HIV seronegative pregnant and nonpregnant control participants (p ≤ 0.001, respectively)." (PMID 33193759, 2020).
malaria (continued). "Malaria disease was the single KEGG pathway identified and this was linked to IL6, syndecan-2 (SDC2) and thrombospondin-1 (THBS1) DEGS that were enriched in the down-regulated gene set." (PMID 31792230, 2019). "Co-infection led to synergistic stimulation of pro-inflammatory (IFN-γ, TNF-α), and anti-inflammatory (IL-6, and IL-10) cytokine responses relative to malaria mono-infection." (PMID 31687034, 2019). "While peripheral levels of TNF-α, IL-1β and IL-6 were similar in women with Malaria and CHB, the pro-inflammatory cytokines were significantly increased in those with Malaria+CHB, which further suggests a possible additive effect of the infections." (PMID 31002731, 2019). "A correlation between high levels of IL-6 with mortality rate has been reported in systemic bacterial infection in humans and dogs, in malaria and canine babesiosis." (PMID 30843407, 2019). "Inflammatory cytokines such as IL-1, IL-6, and IL-10 have been documented in malaria induced thrombocytopaenia." (PMID 31110658, 2019). "The HAT cases expressed significantly higher plasma IFN-γ, IL-6 and IL-10 levels than malaria cases in this study." (PMID 31687034, 2019). "There was an associated increase in IL1-β (P = 0.03), IL-6 (P = 0.001), CXCL1 (P = 0.001) and MCP-1 (P = 0.003) serum levels in malaria-infected mice, when compared to the control group, on GD18.5." (PMID 31391498, 2019). "Cases with HAT and/or malaria parasites responded with an overall increased secretion of anti-inflammatory cytokines (IL-6, IL-10 and TGF-β)." (PMID 31687034, 2019). "It is well known that regulation of pro-inflammatory (IFN-γ, TNF-α, IL-6, IL-17) and anti-inflammatory (IL-10, IL-4) cytokines play a pivotal role in malaria parasite growth, protection, and/or pathogenesis." (PMID 29892278, 2018). "Patients infected with P. vivax or P. falciparum presented an increase in IFN‐γ, TNF‐α, IL‐6, IL‐8, IL‐10, IL‐13, MIP1β, and G‐CSF levels during the malaria acute phase." (PMID 29314720, 2018). "Malaria-induced antibody production and pathology were unaltered by 11β-HSD1 deficiency though plasma levels of IL-4, IL-6 and TNF-α were slightly affected by 11β-HSD1 deficiency, dependent on the infecting parasite." (PMID 29062028, 2017). "All three malaria types had significantly (P < 0.001) lower IL-6 levels (medians, 1.90 pg/ml for UCM, 2.09 pg/ml for SMA, and 1.87 pg/ml for CM) in convalescence than in acute infection." (PMID 28122790, 2017). "IL-6 levels in all three malaria types (medians, 17.31 pg/ml for UCM, 12.20 pg/ml for SMA, and 156.3 pg/ml for CM) were significantly (P < 0.001) higher during acute disease than in controls (2.37 pg/ml)." (PMID 28122790, 2017). "Among the three malaria types, CM patients had the highest IL-6 levels and the differences between the levels in acute SMA and CM and between acute UCM and CM were significant (P < 0.001)." (PMID 28122790, 2017). "High levels of these cytokines were observed in uncomplicated cases, while low IL-6 levels were observed in patients with complicated malaria." (PMID 28118834, 2017). "While there is a paucity of data on this receptor in the literature with regards to human malaria, blockade of trans-signaling by IL-6, of which sIL-6Rβ is the crucial mediator, has been shown to protect against malaria-induced lethality in mice." (PMID 28369062, 2017). "According to this study, IFN-γ, IL-2, IL-5, IL-6 and IL-12 were increased in mild malaria whereas TGF-β, TNF, IL-10 and IL-1β were particularly elevated in CM." (PMID 28775960, 2017). "In malaria patients, the levels of IL-6 and IL-10 were increased expressively in relation to other cytokines, supporting what was noted in other studies on non-complicated malaria." (PMID 27581163, 2016). "The levels of TNF, IL-6 and IL-10 also increased in the serum of the same three groups during blood stage Malaria." (PMID 27446022, 2016).
malaria (continued). "The data presented here demonstrate that high levels of the circulatory pro‐inflammatory, TNF‐α, and IL‐6, are indicators of malaria severity, whereas anti‐inflammatory cytokine IL‐10 level does not differentiate SM and MM cases." (PMID 27042299, 2016). "The data analysis demonstrated that both malaria groups have significantly increased levels of IL-2, IL-4, IL-6, IL-10, TNF and IFN-γ as compared to the endemic controls." (PMID 27581163, 2016). "We conducted this study to explore expression of CD11a, CD11b, CD11c, CD18, HLA‐DR, CD86, TLR‐2 and TLR‐4 and production of TNF‐α and IL‐6 by monocytes in Malawian children presenting with different clinical forms of malaria." (PMID 27027867, 2016). "Pro‐inflammatory cytokines, such as TNF‐α and IL‐6 which are produced by monocytes among other cells, are elevated in severe malaria and appear to be important for controlling infection." (PMID 27027867, 2016). "Hepcidin was positively correlated with IL-6 and IL-10 in the mild malaria group in the present study." (PMID 26466783, 2015). "We have previously shown that C5a can enhance pro-inflammatory cytokine responses, including IL-6, to malaria-infected erythrocytes." (PMID 26402732, 2015). "Hepcidin levels are increased in cases of both severe malaria and malaria with hyperbilirrubinemia, and hepcidin levels are positively correlated with IL-6 and IL-10 in the mild malaria cases, and with IFN-γ in severe malaria subjects." (PMID 26466783, 2015). "IFN-γ and TNF showed the highest relative number of network interactions in the severe malaria group and IL-1β and IL-6 showed the highest relative number of interactions in the hyperbilirubinaemia group." (PMID 26466783, 2015). "Hepcidin was positively associated with IL-6, IL-10, and parasitaemia in the mild malaria group and with IFN-γ in the severe malaria group, which suggests a possible role of immunological regulation in the expression of this hormone." (PMID 26466783, 2015). "The malaria patients who died had significantly raised levels of IL-6 (p = 0.006), IL-8 (p = 0.001), MCP-1 (p = 0.012), and MIP-1β (p = 0.010) compared with the survivors." (PMID 25503583, 2014). "The levels of IL-6 and IL-10 were evaluated in patients presenting the first episode of malaria, patients reporting less than five or more episodes of the disease." (PMID 24741587, 2014). "Course and outcome of both human and experimental blood-stage malaria critically depend on a finely tuned balance between both pro-inflammatory cytokines, as, e.g., IL-1β, TNFα, IFNγ, IL-6, and IL-12, and anti-inflammatory cytokines such as IL-4 and IL-10." (PMID 25408684, 2014). "While the levels of IL-10 and IL-6 were found independent on the number of malaria episodes, higher levels of these cytokines were seen in patients with higher parasite load." (PMID 24741587, 2014). "In lethal P. chabaudi malaria, there occurs biphasic, two-wavy increase in serum IL-1β, TNFα, and IL-6 with the first wave peaking on day 1 p.i. and the second wave peaking at maximal parasitemia on day 8 p.i.." (PMID 25408684, 2014). "The results reported here revealed that a combination of DDX39B, TNF and IL6 host genotypes were associated with manifestations of malaria, mainly by altering plasma levels of TNF and IL-6." (PMID 25038626, 2014). "Before the malaria season, children's immune cells responded to iRBCs by producing pro-inflammatory mediators such as IL-1β, IL-6 and IL-8." (PMID 24743880, 2014). "Different from IL-6 and CXCL-8, evidences suggest that exacerbated levels of IFN-γ are directly correlated with the severity of the malaria caused by P. vivax and the more severe the symptoms are the lower levels of IL-10 are produced." (PMID 24741587, 2014). "The use of principal component analysis and cluster analysis associated increased levels of IL-6, TNF-α, IL-10, and CRP and low levels of IL-17A predominantly with individuals with malaria alone and coinfected individuals." (PMID 25309052, 2014).
malaria (continued). "Immigrants and travelers with malaria had higher levels of IFN-γ, IL-6, and IL-10 (P<0.0100) than patients with other diseases, and IL-8 and IL-1β were elevated in immigrants with malaria (P<0.0500)." (PMID 23967342, 2013). "Reports have been shown that ex vivo explants of foetal tissue from malaria-positive placentas secreted significantly amounts of IL-6 and IFN-γ compared to uninfected placentas and its levels has been associated with low birth weight." (PMID 24237643, 2013). "Up-regulated TGF-β, IL-6, or TNF are associated with a higher frequency of malaria complications and an overall poor malaria prognosis." (PMID 24188121, 2013). "Of note, in all subgroups of children with severe malaria plasma concentrations of IL6, IL10 and TGFβ were reduced in the presence of endotoxaemia compared to those without endotoxaemia." (PMID 23497104, 2013). "IL-1 also inhibits the intra-hepatocytic development of the rodent malaria parasite P. yoelii, an effect partly mediated by IL-6 secretion, and controls blood stage parasitemia in mice infected with P. berghei." (PMID 24130857, 2013). "Gene network analysis of TGFB1/IL-6 or IL-17-related gene expression after malaria infection also suggested that malaria was TH17 dependent." (PMID 24188121, 2013). "Whilst cytokine profiles were similar amongst children in different subgroups of severe malaria, IL6, was higher in the subgroup with shock (Mann Whitney U test, p<0.016)." (PMID 23497104, 2013). "Significantly higher levels of IL-6 were measured in malaria - free placentas than in malaria infected placentas." (PMID 26623293, 2012). "IL6 levels in sera samples from malaria infected placentas (24.4 pg/mL) were significantly reduced (P < 0.05) compared to levels in sera samples from malaria negative placentas (57.5 pg/mL)." (PMID 26623293, 2012). "In this model of malaria, all the inflammatory cytokines (TNFα, IFNγ, IL-1, IL-6, IL-18, IL-10) were found to be significantly elevated in the systemic circulation." (PMID 23323093, 2012). "We found significantly elevated protein concentrations of IL-10, monocyte chemoattractant protein-1 (MCP-1), IFN-γ, TNF-α and IL-6 in lungs, spleens, livers as well as sera of malaria-tuberculosis co-infected mice." (PMID 23110184, 2012). "Uninfected olive baboon placentas expressed significantly higher levels of IL-4, IL-6 and IL-10 compared to malaria infected placentas, indicating that higher levels observed in this panel of cytokines were maintained in uninfected placentas." (PMID 26623293, 2012). "Decreased expression of IL-6 and transforming growth factor–b1 were found in malaria-infected placentas compared with uninfected placentas." (PMID 26623293, 2012). "IL-6 has been shown to be elevated in Mali children with severe P. falciparum malaria, in a study of severe cases of malaria among 40 adults aged 21–65, and has been found elevated in patients with cerebral malaria and renal failure." (PMID 22554058, 2012). "As confirmed here, TNF is significantly upregulated in the malaria-infected placenta, and we show for the first time a significant increase in IL-6 expression with PM." (PMID 22347435, 2012). "Serum cytokines (IL-6 and IL-10), which have previously been shown to be elevated in children with cerebral disease compared to children with alternate severe malaria diagnoses, were examined." (PMID 21447146, 2011). "We previously examined a large panel of inflammatory cytokines and determined that IL-6 and IL-10 levels corresponded to both severity of malaria and cerebral malaria." (PMID 21447146, 2011). "The liver stages of malaria parasites are inhibited by cytokines such as interferon-γ or Interleukin (IL)-6." (PMID 21394207, 2011).